BRCA2 (BRCA2 DNA repair associated)
Diseases named in the same sentence as BRCA2 in open-access papers (continued):
Sharing a sentence is not in itself a finding about the gene and the disease.
breast cancer (continued). "Inhibition of BRCA1 and BRCA2 expression by FR suggested a synergistic cytotoxic effect with olaparib based on the fact that this PARP1 inhibitor is effective in breast cancer with genetic deficiencies in BRCA1 or BRCA2." (PMID 30719229, 2019). "BRCA1 and BRCA2 pathogenic variants were identified in 12.6% (97/768) of breast cancer patients, whereas, 2.5% (19/768) of the individuals carried a variant in another high risk gene and 9.7% (74/768) in a moderate/low penetrance gene." (PMID 31159747, 2019). "Hereditary and genetic factors including mutations in the BRCA1 and BRCA2 genes and other breast cancer susceptible genes account for 5%–10% of breast cancer cases." (PMID 31759379, 2019). "Cumulative lifetime risks (until age 80 years) of breast cancer associated with BRCA1/BRCA2 mutations are estimated to be as high as 72% (65–79%) and 69% (61–77%), respectively, while ovarian cancer risks are 44% (36–53%) and 17% (11–25%)." (PMID 30689103, 2019). "Germline BRCA1/BRCA2 pathogenic variants are an important factor in studying young women with breast cancer." (PMID 31491032, 2019). "One possible mechanism of carcinogenic action of BLV and its close relative HTLV (human T-cell leukemia virus) is inhibition of cellular DNA repair, consistent with how certain mutated genes (BRCA1 and BRCA2) contribute to the development of breast cancer." (PMID 31892207, 2019). "In contrast, male breast cancer patients harboring BRCA2 mutations (n=4) had an older mean age of diagnosis than non-carriers (n=22) (66.5 years (range 54-76) and 52.5 years (range 27-69) years, respectively, p=0.039, Wilcoxon rank-sum test)." (PMID 31528241, 2019). "Pathogenic BRCA1 and BRCA2 variants were identified in 7% of the investigated patients with breast cancer." (PMID 31263571, 2019). "BRCA1 and BRCA2 germline mutations have been shown to play a significant role in genetic predisposition to breast cancer." (PMID 31131559, 2019). "The polymorphic site, ATF1 rs11169571, was analyzed in a group of ovarian/breast cancer patients with BRCA1 or BRCA2 mutation." (PMID 30905073, 2019). "Loss of E2F7 confers resistance to poly-ADP-ribose polymerase (PARP) inhibitors in BRCA2-deficient breast cancer cells." (PMID 31703415, 2019). "Our patient with leptomeningeal metastasis in the setting of BRCA2-mutated breast cancer has maintained a complete clinical and a robust radiographic response to olaparib after 19 months of therapy." (PMID 31815182, 2019). "In unselected TNBC cases, the prevalence of pathogenic germline BRCA1 and BRCA2 mutations is approximately twice as high as in breast cancer overall." (PMID 31683572, 2019). "During the surveillance period, 5 individuals with BRCA1 or BRCA2 mutations were diagnosed with primary breast cancer." (PMID 30980249, 2019). "When BRCA1/BRCA2 mutation carriers were diagnosed before age 40 years, the risk of a contralateral breast cancer (CBC) reached nearly 50% in the ensuing 25 years." (PMID 30652428, 2019). "Herein we report a novel pathogenic variant in BRCA2 in a consanguineous family with a family history of breast cancer." (PMID 31060517, 2019). "While the frequency of pathogenic variants in BRCA1 and BRCA2 is high in the Ashkenazi Jewish population, it was found that 0.3% of all Ashkenazi Jewish breast cancer patients were double heterozygotes for BRCA1/2 pathogenic variants." (PMID 31395037, 2019). "For carriers of the BRCA2 mutation, the risk of ovarian cancer is 11%–16.5%, and the risk of breast cancer is 45%–55%." (PMID 31818005, 2019).
breast cancer (continued). "Poly(ADP-ribose) polymerase (PARP) inhibition is used in the clinic to kill HR-deficient tumor cells such as cells mutated for the breast cancer predisposition genes BRCA1 or BRCA2 by synthetic lethality." (PMID 31584931, 2019). "Previous studies have associated the trinucleotide repeat polymorphism (CAGn) in the exon 1 of the androgen receptor gene (AR) and mutations in BRCA1 and BRCA2 with breast cancer among Filipino women." (PMID 31030479, 2019). "For instance in breast cancer, a women can inherit a BRCA1/BRCA2 mutation, which gives her a life-time elevated risk of breast cancer of 50–85%." (PMID 30781705, 2019). "Inhibition of BRCA1 and BRCA2 gene expression suggested a synergistic cytotoxic effect with PARP1 inhibitor based on previous findings in breast cancer with mutation of BRCA1 or BRCA2." (PMID 30719229, 2019). "A 48-year-old woman with a BRCA2 mutation developed DCIS as a primary breast cancer during surveillance 3 years after genetic testing." (PMID 30980249, 2019). "BRCA1 and BRCA2 mutation patients had a respective 4.5- and 3.4-fold elevated risk of developing contralateral breast cancer." (PMID 31998630, 2019). "Hereditary and genetic factors, such as a personal or family history of breast cancer and some inherited mutations, BRCA1 and BRCA2, are important predictors of the development of breast cancer." (PMID 31578436, 2019). "To clarify the BRCA1 L63X founder mutation, we compared the three groups (BRCA1 L63X, other BRCA1 mutations, and BRCA2 mutations) of breast cancer patients." (PMID 31143373, 2019). "BRCA1- and BRCA2-deficient breast cancers were further shown to have higher number of mutations and correspondingly and higher number of predicted neoantigens." (PMID 31022191, 2019). "Apostolou and Fostira (2013) claimed hereditary and genetic factors including mutations in the BRCA1 and BRCA2 genes and other breast cancer susceptible genes account for 5%–10% of breast cancer cases." (PMID 31759379, 2019). "The limitation of our study was the small number of BRCA1- and BRCA2-deficient breast cancers relative to BRCA-proficient breast cancers." (PMID 31022191, 2019). "Among all genes involved in DNA repair pathways, BRCA1 and BRCA2 genes are characterized by a particular association with breast cancer." (PMID 31405066, 2019). "Of 78 total patients, 15 had BRCA1 mutation-associated breast cancer and 12 had BRCA2 mutation-associated breast cancer." (PMID 30934991, 2019). "The differences in immunophenotype between BRCA1- and BRCA2-deficient breast cancers can be attributed, in part, to PTEN gene mutation." (PMID 31022191, 2019). "Taken together, BRCA1- and BRCA2-deficient breast cancers demonstrated higher degree of genomic instability compared to BRCA-proficient breast cancers." (PMID 31022191, 2019). "On the other hand, tumors arising in BRCA2 mutation carriers reveal a phenotype distribution mirroring spontaneous breast cancers." (PMID 31225507, 2019). "Our results suggest that there are challenges involved in the early detection of breast cancers in BRCA1 or BRCA2 mutation carriers." (PMID 30980249, 2019). "The features genomic instability observed in both BRCA1- and BRCA2-deficient breast cancers suggests that these cancers would demonstrate similar gene expression signatures and immune features." (PMID 31022191, 2019). "Harmful mutations in the BRCA1 and BRCA2 genes can produce very high rates of breast and ovarian cancer and increases the risk of developing breast cancer by up to 85% and the ovarian cancer by up to 54%." (PMID 30898109, 2019). "Women with BRCA1 or BRCA2 mutations strongly expressed preferences for breast cancer risk reduction and preservation of fertility." (PMID 30980249, 2019).
breast cancer (continued). "Advances in molecular biology in recent decades have resulted in the identification of genes, such as the tumor suppressor genes BRCA1 and BRCA2, that, when altered, significantly increase the risk of developing breast cancer, ovarian cancer, and other tumors." (PMID 31244284, 2019). "Investigating BRCA1 and BRCA2 mutation status in ovarian and breast cancer tissues patients, has a key role in addressing the therapeutic choices." (PMID 31065452, 2019). "In subjects carrying a germline mutation in the BRCA1 gene, the risk of developing breast cancer is around 70–80% and for the BRCA2 gene it is 50–60%." (PMID 31405066, 2019). "Increased PD-L1 expression is identified in breast tumors deficient in DNA repair, and infiltrating immune-cell PD-1 and PD-L1 expression is higher in breast cancers with BRCA1 or BRCA2 mutations." (PMID 31320901, 2019). "A similar chemical library screen aiming to identify drugs that target BRCA2‐deficiency was previously performed using Brca2−/− mouse mammary tumour‐derived cell lines and the LO‐PAC®1280 Sigma library of pharmacologically active compounds (Dataset EV1)." (PMID 31273933, 2019). "Five of the 26 individuals with BRCA1 or BRCA2 mutations were diagnosed with primary breast cancer while undergoing surveillance." (PMID 30980249, 2019). "It is shown to reduce breast cancer risk by at least 95% in women with BRCA1 or BRCA2 mutation and by 90% for those with a strong family history." (PMID 31267556, 2019). "Here we report a case of a patient with BRCA2-mutated breast cancer and solitary recurrence in the leptomeninges with ongoing complete response to treatment with the PARP inhibitor olaparib." (PMID 31815182, 2019). "It is noteworthy that an on-going clinical trial is investigating pembrolizumab, an anti-PD-1 antibody, in advanced BRCA1- and BRCA2-mutated breast cancer patients (ClinicalTrials.gov identifier: NCT03025035)." (PMID 31022191, 2019). "In the current study, we also did not observe a survival benefit associated with oophorectomy in women with BRCA2-associated breast cancer." (PMID 30723304, 2019). "Patients with BRCA1 and BRCA2 mutations have up to an 87 per cent lifetime risk of developing breast cancer." (PMID 30957063, 2019). "In our study, we found a BRCA1/2 mutation prevalence of 19.5% (BRCA1 = 9.75% and BRCA2 = 9.75%) in breast carcinoma patients under the age of 40 years old." (PMID 30713775, 2019). "One carcinoma center found a BRCA1/2 mutation prevalence of 23% (BRCA1 = 17% and BRCA2 = 6%) in breast carcinoma patients under 35 years old." (PMID 30713775, 2019). "The breast cancer 1 gene (BRCA1) and the breast cancer 2 gene (BRCA2) are the two most-studied BC susceptibility genes." (PMID 30940775, 2019). "The presence of germline and somatic deleterious mutations in the BRCA1 and BRCA2 genes has important clinical consequences for breast cancer (BC) patients." (PMID 31454914, 2019). "The guidelines recommend considering the BRCA1 and BRCA2 germline mutations in female patients with breast carcinomas." (PMID 30713775, 2019). "While cisgender men have a lifetime risk for breast cancer of 0.1%, those with Klinefelter’s syndrome or a deleterious mutation of the BRCA2 gene have an elevated lifetime risk for breast cancer of 5–7%." (PMID 29392096, 2018). "Our finding was consistent with previous reports that high BRCA2 mRNA levels are associated with an aggressive phenotype of sporadic breast cancer." (PMID 29321957, 2018). "In 2005, two landmark studies showed that PARPi selectively killed breast cancer allele 1 or breast cancer allele 2 (BRCA1/BRCA2)-deficient cancer cells by inducing the collapse of replication forks." (PMID 30680069, 2018). "Here we explored the therapeutic benefit of combining everolimus to a PARP inhibitor in two different patient-derived xenografts of BRCA2-mutated breast cancer with genomic alterations in the PI3K pathway." (PMID 30038706, 2018).
breast cancer (continued). "Two individuals with breast cancer (4.2% of cases) and one with ovarian cancer (5.3% of cases) carried germline BRCA2 mutations." (PMID 29464067, 2018). "At the end of follow-up, 15 mutation carriers (12 BRCA1 and 3 BRCA2) exposed to ovarian stimulation for IVF had developed breast cancer." (PMID 29937543, 2018). "BRCA1 and BRCA2 mutations confer a substantial breast risk of developing breast cancer to those who carry them." (PMID 30103738, 2018). "The next-generation sequencing analysis revealed the presence of breast cancer gene 2 (BRCA2) somatic mutation and an increased somatic mutational load without microsatellite instability (MSI)." (PMID 30547773, 2018). "In this study we tested the combination of two FDA-approved drugs, olaparib and everolimus, in PDX models established from BRCA2-mutated breast cancer carrying molecular alteration in the PI3K pathway." (PMID 30038706, 2018). "An example of such a variant is BRCA2 p.K3326X, which is classified as benign in the ClinVar and Breast Cancer Information Core (BIC) databases." (PMID 30040829, 2018). "Germline mutations in either the BRCA1 or BRCA2 (BRCA1/2) gene account for approximately 2–3% of all breast cancer, but around 30% of hereditary breast cancer." (PMID 30544963, 2018). "Hereditary factors such as germline deleterious mutations in BRCA1 and BRCA2 genes significantly increases predisposition to breast cancer." (PMID 29713003, 2018). "BRCA2-rs4987047 is the only rare exonic variant identified on the known breast cancer susceptibility genes." (PMID 29879995, 2018). "Mutations in the BRCA1 and BRCA2 genes remain by far the most common genetic explanation for a strong family history of breast cancer." (PMID 29039119, 2018). "When we performed a gene-based test, BRCA2 was significantly associated with male breast cancer (18.9% in cases and 0.2% in controls, Fisher’s exact test, P = 1.73 × 10−16, OR = 111.2)." (PMID 30287823, 2018). "With BRCA2 mutations, the probabilities are at 45–49% for breast cancer and 11–18% for ovarian cancer." (PMID 29459887, 2018). "The BRCA1 c.5470_5477delATTGGGCA and BRCA2 c.7878G>A were the most prevalent mutations among Chinese breast cancer patients that reside in US and other countries." (PMID 29487695, 2018). "BRCA1 and BRCA2 are major breast cancer susceptibility genes whose pathogenic variants are associated with a significant increase in the risk of breast and ovarian cancers." (PMID 30453575, 2018). "BRCA2, the second major hereditary breast cancer susceptibility factor, is also critical for maintaining genome integrity." (PMID 29718910, 2018). "Women with BRCA1 and BRCA2 mutations who receive bilateral total salpingo-oophorectomy at or before the age of 40 benefit from a 40% reduction in the risk of breast cancer." (PMID 29713580, 2018). "The present study demonstrates a clear protective effect of early first pregnancy on breast cancer risk in women with pathogenic BRCA1 or BRCA2 mutations." (PMID 29116468, 2018). "The risk for women with BRCA1- and BRCA2-positive breast cancer of developing primary ovarian cancer is 15–65%." (PMID 29177593, 2018). "Women who inherit a deleterious germline BRCA1 or BRCA2 mutation face high lifetime risks of developing breast cancer by age 80, which are estimated at 72% and 69%, respectively." (PMID 30572612, 2018). "The pathology of consecutive breast cancers related to those variants were estrogen receptor-positive as typically described for BRCA2 breast tumors (29/35 ER-positive, 32/35 PR-positive, 4/18 HER2-positive, 10/25 grade 2)." (PMID 29707112, 2018). "The information reviewed in the Clinical Variation database showed that the BRCA1 and BRCA2 pathogenic variants found in our study have been reported in patients with breast cancer or ovarian cancer patients." (PMID 29997359, 2018).
breast cancer (continued). "They included 1380 women with a BRCA1 or BRCA2 mutation with a history of breast cancer (cases) and matched them to 1380 female BRCA1 or BRCA2 mutation carriers without a history of breast cancer (controls)." (PMID 29937543, 2018). "Consistent with our local data, BRCA2 mutation predominance was seen in overseas Chinese breast cancer patients." (PMID 29487695, 2018). "In vitro experiments performed in two breast cancer cell lines, one showing a BRCAness phenotype due to a BRCA2 mutation, show an increased synergy between olaparib and everolimus in the BRCA2 mutated cell line as compared to the BRCA wild-type." (PMID 30038706, 2018). "Penetrance of the mutations involving the BRCA1 gene and breast cancer is more expressive than that for the BRCA2 gene and ovarian cancer." (PMID 30517521, 2018). "We identified only 2 BRCA2 variants: c.9334G>A in one out of 96 MM early-onset families and c.4534 C>T in one out of 30 families with aggregation of MM and breast cancer." (PMID 30286154, 2018). "For BRCA1 mutation carriers, the risk of breast cancer increased substantially between the ages of 30–50, while for women with a BRCA2 mutation, the risks were highest between ages 40–60." (PMID 30572612, 2018). "Pathogenic mutations in BRCA1 and BRCA2 genes explain ~ 30% of the cases of families with a high risk of cancer and ~ 15% of breast cancer familial relative risk." (PMID 29678143, 2018). "While the present article was under review, a study was published claiming that the BRCA2 c.68‐7T > A variant was associated with breast cancer." (PMID 29460995, 2018). "Second, the subgroup of BRCA2 mutation carriers was too small for a separate analysis (only three exposed BRCA2 mutation carriers were diagnosed with breast cancer)." (PMID 29937543, 2018). "Men with a BRCA2 mutation have elevated risks for prostate cancer (up to 39%) and breast cancer (up to 10%)." (PMID 30001421, 2018). "As for BRCA2, it was considered as a susceptibility gene whose mutation was frequently found in breast cancer and ovarian cancer." (PMID 29891014, 2018). "BRCA2 mutated breast cancers are mostly luminal B (73%), while luminal A and basal-like breast cancer account for only 14% and 9%, respectively." (PMID 30038706, 2018). "In the present study, we analyzed the BRCA2 c.68‐7T > A variant, located in the proximity of the acceptor site of exon 3, in order to establish its clinical relevance and association with breast cancer risk." (PMID 29460995, 2018). "A recently published multicenter study indicates that carriers of this variant have an increased risk of developing breast cancer and ovarian cancer independently of other pathogenic variants in BRCA2." (PMID 30040829, 2018). "In women who carry the BRCA1 mutation the chances of getting breast cancer are around 65% and with BRCA2 they are around 40% (AIOM)." (PMID 30061853, 2018). "As a result of the largest study, the Breast Cancer Linkage Consortium (BCLC) reported an approximate 2.6-fold increase in the risk for CMM among BRCA2 mutant carrier families." (PMID 30286154, 2018). "Screening to identify BRCA1 and BRCA2 carriers is especially important because there are several preventative options which can lower the risk of developing breast cancer." (PMID 29713580, 2018). "One of these, the hereditary breast and ovary cancer syndrome (HBOCS), associated with germline mutations in BRCA1 and BRCA2 genes, is believed to cause approximately 10–15% of all breast cancers (BCs)." (PMID 29456621, 2018). "Male breast cancer is rare in the general population with a lifetime risk of 0.1%, although the risk is significantly increased to 7-8% with BRCA2 mutation and 1% with a BRCA1 mutation." (PMID 29433453, 2018). "Kuchenbaecker, in a recent study, showed that the BRCA1 risk of breast cancer was estimated at 72% and BRCA2 at 69%." (PMID 30340058, 2018).